ICOS (inducible T cell costimulator)
Diseases named in the same sentence as ICOS in open-access papers (continued):
Sharing a sentence is not in itself a finding about the gene and the disease.
cancer (continued). "It is worth noting that the Kaplan-Meier cumulative curve shows that in the TCGA database, the expression of ICOS(CD278) is related to the prognosis of several cancers." (PMID 36855091, 2023). "Anti-ICOS agonists were already tested in mice studies and in clinical trials for cancer immunotherapy, and show promising results when used in combination with other checkpoint inhibitors like anti-PD-1 and anti-CTLA-4 antibodies." (PMID 37056774, 2023). "The ARMG risk score showed significantly positive relation with immunoinhibitors TGFB1 and VTCN1, and was negatively related with immunostimulators CD27, CD28, CD40LG, CD80, ENTPD1 and ICOS in pan-cancer." (PMID 38090588, 2023). "ICOS was positively correlated with at least one DNMTs expression in 19 cancers, and negatively correlated with DNMT expression in 5 cancers." (PMID 36855091, 2023). "Compared to cancer patients who received therapies other than anti-PD-1 antibodies or healthy control individuals, patients with cancer receiving anti-PD-1 antibodies exhibited a 2.6-fold expansion of ICOS+CD38+ Tfh cells on average one week after vaccination." (PMID 36380097, 2023). "mAbs targeting CTLA4, PDCD1, CD274, and LAG3 have been approved by the FDA for second- and first-line treatment against cancer, whereas mAbs targeting ICOS and CD40 are under investigation." (PMID 37215135, 2023). "To further study the potential mechanism of immunosuppression of the ICOS signaling pathway, in 33 different cancer types, we looked at the relationship between ICOS expression and immunological checkpoint markers.." (PMID 36855091, 2023). "The results illustrated that CTLA4 and ICOS were negatively correlated with DDR1 among 19 cancers while positively correlated with DDR1 in LAML and LIHC." (PMID 37031216, 2023). "The findings demonstrate that ICOS has the potential to be employed as a prognostic biomarker in a variety of cancer types." (PMID 36855091, 2023). "We demonstrate, consistently, that ICOS is expressed in a range of cancers, and its induction can stimulate growth of antitumor reactive T cells." (PMID 37593752, 2023). "In this study, a pan-cancer analysis workflow was carried out, and the role of ICOS in cancer was studied in depth." (PMID 36855091, 2023). "The result is that the expression of malignancy was revealed by the immune cells’ invasion.profile of ICOS in different types of cancer." (PMID 36855091, 2023). "The associations of P4HA1 expression with LAG3, ICOS, CTLA4, CD48, TNFSF14, and CD27 expression were inconsistent among cancer types." (PMID 35812752, 2022). "We further demonstrated that high PRKCI expression in PDAC is associated with reduced activation of several immune signaling pathways implicated in the improved survival of PDAC cancer patients, including OX40, iCOS, and Th1 signaling." (PMID 35159064, 2022). "The abnormality of ICOS expression leads to a range of pathophysiological dysfunctions, such as immunodeficiency, opportunistic infection, and malignant tumors." (PMID 36276141, 2022). "In tissue, Tregs and ICOS+ Tregs were found distributing mainly in carcinoma tissue, whereas pDCs were mainly found in peritumor tissue." (PMID 35311157, 2022). "The Foxp3+ICOS+/Foxp3+ cell ratio in carcinoma and peritumor tissue were higher than that in normal tissue." (PMID 35311157, 2022). "Additional engineering of CAR T-cells to include intracellular signaling motifs from costimulatory molecules such as CD28, 4-1BB, OX40, and ICOS serve to enhance their proliferation and ability to eradicate cancer cells and cytokine production." (PMID 33442419, 2021). "TIGIT expression also positively correlated with CTLA4, PDCD1 (PD-1), CD274 (PD-L1), ICOS in most of the cancer types." (PMID 34795387, 2021). "It has also been reported that ICOS and CTLA4 lead to disturbances of the immune response and thereby indicate an increased risk of cancer." (PMID 33869632, 2021).
cancer (continued). "The blockage of ICOS pathway has been shown to inhibit the activity of Type 2 T helper cells, thus potentially protecting against cancer growth." (PMID 31143539, 2019). "miR-101 has been associated with inflammation as a negative regulator of inducible costimulator (ICOS) and cancer cell stemness as a negative regulator of the corepressor C-terminal binding protein-2 (CtBP2)." (PMID 25886994, 2015). "ICOS acts as a ligand of programmed death-1 (PD-1) on T cells, induces the immune escape of cancer cells and also acts as a receptor mediating anti-apoptotic effects on cancer cells." (PMID 25789052, 2015). "B7-H1 is a ligand of inhibitory inducible co-stimulator (ICOS) that is broadly expressed on various human cancers." (PMID 25789052, 2015). "Previous studies in cancer patients and animals have suggested that ICOS+ T cells play an important role in the action of anti-CTLA-4, as well as having prognostic significance." (PMID 23626745, 2013). "Benefiting of the activatory effect of ICOSL/ICOS pathway in the context of cancer therapy was evaluated." (PMID 23450201, 2013). "Therefore, further investigation with large-scale cohort studies across the diverse types of irAEs, cancers, and regimens will be necessary to validate the importance of ICOS+CD4+ T cells and CXCL13 in irAE development." (PMID 40198121, 2025). "Based on our findings, bispecific PD-L1 and ICOS inhibition will efficiently inhibit activated Tregs, which may contribute to the immune escape of cancer cells to evade host immune surveillance." (PMID 40650080, 2025). "As a result, the role and prognostic significance of ICOS may be different depending on the type of cancer, underscoring the importance of ongoing critical inquiry into its function." (PMID 39201462, 2024). "The results showed that ICOS expression was up-regulated in most cancer tissues." (PMID 38616999, 2024). "Therefore, the expression of ICOS in many series has a variable impact on prognosis depending on the type of cancer." (PMID 38616999, 2024). "The fact that the extracellular domain PD‐1 shares 21%–33% sequence identity with ICOS, which indicates that ICOS might play an important role in regulating immune microenvironment of cancer." (PMID 38506253, 2024). "Indeed, ICOS exhibits less potency when targeted alone compared to other pathways commonly addressed in cancer immunotherapies." (PMID 39684559, 2024). "The ICOS mRNA expression was evaluated in the 33 cancer types." (PMID 38616999, 2024). "ICI therapy has proven to be a useful treatment for carcinoma, and we observed that the risk score was negatively correlated with the immune checkpoints CTLA4, ICOS, and PDCD1, suggesting that the sensitivity to immunotherapy may differ among subgroups." (PMID 38244579, 2024). "The findings revealed that ICOS expression was up regulation in most cancer types." (PMID 36855091, 2023). "According to this study, ICOS may be used as a cancer biomarker for prognosis and a possible therapeutic target." (PMID 36855091, 2023). "In a variety of cancers, the expression of ICOS is also related to TMB, MSI, DNMTS, and MMR genes." (PMID 36855091, 2023). "In diverse types of cancer patients, our investigation discovered a connection between DNMTs and ICOS expression, and DNA methylation may also be involved in the regulation of ICOS." (PMID 36855091, 2023). "Taken together, these analyses suggest that ICOS is a meaningful biomarker in a variety of cancers." (PMID 36855091, 2023). "In recent years, expanding studies suggest that ICOS may be a new therapeutic target in cancer, and there are several clinical trials on ICOS or ICOSL as combination targets with ICIs." (PMID 37850501, 2023). "Tumors and adjacent normal tissues express ICOS differently across a variety of cancer types." (PMID 38127899, 2023).
cancer (continued). "The results of the association between IFN-γ score and ICG indicated that the IFN-γ scores of virtually all of the different cancers that were investigated had a positive association with the expression of TIGIT, IDO1, ICOS, CD86, CTLA4, HAVCR2, PDCD1LG2, and CD48." (PMID 37646041, 2023). "This phenomenon might be explained by the heterogeneity of cancers and the fact that the immune regulatory pattern of ICOS might be vary in different tumors." (PMID 38127899, 2023). "The results show that the prognostic impact of ICOS on different types of cancer." (PMID 36855091, 2023). "In contrast, ICOS had a negative effect on patients with LGG, UVM, and GBM cancers, where higher ICOS expression was associated with a lower survival rate than low ICOS mRNA levels." (PMID 36855091, 2023). "This study shows that ICOS has great prognostic value in different types of cancer." (PMID 36855091, 2023). "Similar to the pan-cancer analysis, LRP2 mutations had high TMB, MSI and immune cell infiltration in EC and also leaded to high expression of immune-related genes, such as CXCL9, CXCR6, CXCL13, ICOS and immune checkpoint genes (CTLA4 and LAG3)." (PMID 35834061, 2022). "While ICOS has been studied in other cancers, its role in EOC has yet to be well-elucidated." (PMID 33747935, 2021). "In contrast, the expression of genes regulating immune cell trafficking (e.g., CXCL13, CXCL9, XCL2, CCL5), T-cell activation and clonal expansion (e.g., CD27, CD28, ICOS, IL21, IL2) were massively decreased in 9p21-loss tumors across multiple cancer types/subtypes." (PMID 34556668, 2021). "Cancer is often linked to an expansion of MDSCs/Tregs, in which OPN/ICOSL/ICOS trio may be involved." (PMID 35052731, 2021). "In the light of the emerging role of the ICOS/ICOSL/OPN trio in cancer progression, inflammation, adaptive immunity, and bone metabolism, this trio might be targeted in various ways in order to influence these processes in several human diseases." (PMID 33106594, 2020). "Numerous trials are exploring immunotherapy combination approaches in advanced cancers with a backbone of PD‐1/PD‐L1/CTLA4 inhibition in conjunction with Treg cell focused agents including those targeting the Inducible T cell Co‐Stimulator (ICOS) receptor (NCT02723955), and GITR (NCT03126110)." (PMID 32383556, 2020). "B7h:ICOS interaction may modulate the spread of cancer metastases, suggesting the novel use of ICOS-Fc as an immunomodulatory drug." (PMID 30669702, 2019). "However, while ICOS agonist therapy holds promise in enhancing antitumor immunity, its potential negative impact due to the critical expression and functional role of ICOS on Tregs underscores the complexity of immune regulation in cancer." (PMID 39684559, 2024). "Although PD-L1 exerts immunosuppressive effects through its interaction with PD-1 and ICOS promotes immune responses by enhancing T-cell activity, they may exhibit crossover or synergistic effects under specific conditions, such as cancer immune escape and immune checkpoint blockade therapy." (PMID 38616999, 2024). "Besides, patients with higher levels of Faecalibacterium demonstrated an increase in the expression of inducible T cell co-stimulator (ICOS) on T cells, which has been reported as a potential biomarker for the effectiveness of ipilimumab treatment in cancer patients." (PMID 38547865, 2024). "However, certain conditions, like chronic viral infections or certain cancer microenvironments, might induce ICOS expression on NK cells, potentially altering their function." (PMID 38283362, 2023). "Moreover, the higher expression of the ICI-related genes (such as ICOS) was observed in the low-risk group, indicating that patients in the low-risk group might have a superior response to the ICI and cancer vaccines than those in the high-risk group." (PMID 35884544, 2022). "On the contrary, blocking its ICOSL/ICOS-mediated suppression may be beneficial in cancer therapy." (PMID 23450201, 2013).
cancer (continued). "The current study evaluated ICOS and ICOSL RNA expression levels in relationship to other ICIs and cancer types." (PMID 40297627, 2025). "Advanced-stage cancers had decreased levels of ICOS expression, and tumors with high ratios of PD-L1/ICOS, PD-L2/ICOS, or CD276/ICOS expression have a worse prognosis and a worse prognosis for patients with positive lymph nodes." (PMID 40661938, 2025). "In contrast, no clinical evidence is available for anti-LAG3, anti-TIGIT, anti-BTLA, anti-ICOS and anti-IDO1 antibodies in MSI-H cancers, but clinical trials are ongoing." (PMID 38254772, 2024). "Of relevance, we demonstrate that the absence of CD28 provides a functional advantage to Ag-experienced (ICOS+, CD137+, CD11ahigh) PD1+CD8+ T cells in the setting of peripheral blood of cancer patients." (PMID 37898752, 2023). "The expression of ICOS mediates infiltration of immune cells and is positive correlated with the expression of PDCD1, CTLA4, and TIGIT in most cancer types." (PMID 36855091, 2023). "However, the function of ICOS(CD278) in pan-cancer remains unknown." (PMID 36855091, 2023). "On the other hand, ICOS/B7-H2 signal enhances secondary responses by CD8(+) T cells and improves effectiveness of cancer therapy." (PMID 36922519, 2023). "This study showed that the ratios of PD-L1 or PD-L2, normalized with ICOS and other CD28 members, also allowed for a good survival prediction for all cancers and HNSCC with nodal involvement in both cohorts using univariate modes." (PMID 36983005, 2023). "Ingenuity pathway analysis (IPA) established the contribution of genes for ICOS-ICOSL, PD1-PDL1, NF-κB, E2F transcription, and molecular mechanisms of cancer-signaling pathways." (PMID 37296831, 2023). "For instance, ICOS has positive relationships with PDCD1, TIGIT, CD274, and CTLA4 in the majority of cancer types, indicating a broad co-expression landscape." (PMID 36855091, 2023). "In our study, focuses were made on the PD-1/PD-L1, ICOS/ICOSL, and GITR/GITRL pathways in cancer cells." (PMID 36160406, 2022). "As previously reported, in the cancer-immunity cycle, CD28: (CD80, CD86), CD40, CD27, HVEM, GITR: GITRL, ICOS, and TLR-2 are stimulatory factors, while TIM-3, PD-L1: PD-1, PD-L1: (CD80, CD86), CTLA-4: (CD80, CD86), BTLA, and LAG-3 are inhibitory factors." (PMID 35419462, 2022). "Our results suggested that in most types of cancer, SERCA3 expression was distinctly related to immune checkpoints, such as TLR4, ICOS, CTLA-4, PDCD1, and CD27." (PMID 36385955, 2022). "Second, most immuno-stimulators, such as MICB, MICA, CD80, ICOS, CD27, and various TNFSFs (all P < 0.05), were expressed at higher levels in PTPRD/PTPRT mutant cancers, compared with the WT." (PMID 36248841, 2022). "In this study, we identified the upregulated miR-related signaling network in LCT-MF including ICOS-ICOSL signaling, PD1-PDL1 signaling, NF-κB signaling, E2F transcription, and molecular mechanisms of cancer pathways." (PMID 34831008, 2021). "A number of T cell costimulatory molecules including CD137, OX40, CD40, ICOS, GITR, and CD27 are being targeted pharmacologically with agonists to improve outcomes in cancer patients." (PMID 34290245, 2021). "Ingenuity pathway analysis (IPA) demonstrated the involvement of genes for ICOS-ICOSL, PD1-PDL1, NF-κB, E2F transcription, and molecular mechanisms of cancer signaling pathways." (PMID 34831008, 2021). "The results showed that the five TLR4 prognosis-related cancers KIRC, SKCM, STAD, TGCT, and UCEC were related to ICOS, CTLA4, CD28, and CD80." (PMID 34631699, 2021). "IPA demonstrated the involvement of relevant genes in pathways of ICOS-ICOSL signaling, PD1-PDL1 signaling, NF-κB signaling, E2F transcription and molecular mechanisms of cancer." (PMID 34831008, 2021). "Based on these preclinical data, the humanized ICOS antibody, JTX-2011, is currently in clinical development as a cancer immunotherapeutic." (PMID 32970735, 2020).
cancer (continued). "OX40 treatment has been reported to increase expression of ICOS on both CD4 and CD8 T-cells, and modulating this pathway can impact the therapeutic response to anti-OX40 antibodies in mouse models of cancer." (PMID 31959281, 2020). "Regarding receptors, there exhibited a strong correlation with PD-1 and receptors including TIGIT, CTLA-4, LAG3, BTLA, ICOS, TNFRSF9, CD27 in most types of cancer." (PMID 30607140, 2018). "ICOS is a co-stimulatory molecule of the CD28-B7 superfamily and its role in cancer is controversial." (PMID 30687714, 2018). "The inducible costimulator (ICOS) is a CD28-related molecule expressed on activated T cells and is capable of interacting with its ligand ICOSL, present on APCs such as like dendritic cells (DCs), B lymphocytes, and certain cancer cells." (PMID 38213479, 2023). "Thus, six major ICs for cancer immunotherapy were analyzed in this work, namely CTLA4, PDCD1, CD274, ICOS, LAG3, and CD40." (PMID 37215135, 2023). "ICOS binds to its unique ligand belonging to the B7 family ICOS-ligand (ICOSL), also named B7H2 or CD275, which is constitutively expressed by APCs and can be induced in many other cell types such as cancer cells." (PMID 37056774, 2023). "Next, we focused on the role of co-stimulatory molecules other than CD28, i.e. ICOS, CD137 (4-1BB), and integrin CD11a as contributors to the functional fitness of PD1+CD28− T cells in peripheral blood of NSCLC cancer patients." (PMID 37898752, 2023). "CD275 (ICOSL), the ligand of ICOS, also a T cell activation marker, was not expressed on cancer cells." (PMID 37762490, 2023). "• Mediate metastatic cancer cells dormancy through cell cycle arrest by IFN-γ and TNF-α.• A significant enrichment of convergent TCR clusters.• Enriched with activated HLA-DR+ and ICOS+ and proliferating KI67+ cells.• A high proportion of HPV-specific T cells." (PMID 36451828, 2022). "Clinical and nonclinical data suggest that ICOS plays an important role in the immune response to cancer." (PMID 32970735, 2020). "Also of notice, a pronounced number of critical immunomodulators, which were described in an immunogenomic analysis of major TCGA cancer data sets and included PDCD1LG2, BTN3A2, GZMA, BTLA, CD28, ICOS, and IDO1, were contained in the 358 DEG set." (PMID 32603365, 2020). "Since ICOS is exclusively expressed on the membrane of T cells, its interaction with ICOSL, located on cancer cell membranes, may be of pathological relevance in mediating immune cell function." (PMID 31143539, 2019). "The activation of the ICOS pathway plays a key role in activating the expansion of Treg and the release of IL-10 by secretion from memory CD4+ T cells, both of which create an immunosuppressive environment for cancer growth." (PMID 31143539, 2019). "Potential synergistic efficacy to boost immunity against cancer may also be implemented as already seen with GITR stimulation/PD-1 blockade and CTLA-4/ICOS stimulation." (PMID 31181772, 2019). "Notably, the analysis highlighted different T-cell activation pathways in different cancer types, particularly the CTLA4, CD28 and iCOS-iCOSL signalling pathways in T cells, which are the key pathways in anti-CTLA-4 immunotherapy treatments." (PMID 26634437, 2015). "In addition, we used CIBEROR and TIMER methods to analyze the correlation of immune infiltrating cells in 33 cancers.Results from the CIBEROR and TIMER databases revealed a correlation between different immune cells and the expression of ICOS in 33 malignancies." (PMID 36855091, 2023). "However, it should be noted that while an increase in ICOS expression in CD8+ T cells and non‐regulatory CD4+ T cells (non‐Tregs) is desirable for anti‐cancer immunity, higher ICOS expression in Tregs has been shown to be more immunosuppressive compared to lower ICOS expressing Tregs." (PMID 36176603, 2022).